RNU6-987P (RNA, U6 small nuclear 987, pseudogene)
Gene: Small nuclear RNA gene on chromosome 6 (25,383,599 to 25,383,702, forward strand). Ensembl gene ENSG00000207490.
Homologues: Orthologues: chimpanzee U6 (99% identical), macaque U6 (88% identical), pig U6 (83% identical), pig U6 (76% identical), pig U6 (75% identical), rabbit U6 (75% identical), dog U6 (73% identical), pig U6 (72% identical), pig U6 (69% identical). Paralogues in human: RNU6-73P (86% identical), RNU6-769P (86% identical), RNU6-16P (85% identical), RNU6-20P (85% identical), RNU6-820P (85% identical), RNU6-1031P (84% identical), RNU6-38P (84% identical), RNU6-854P (84% identical), RNU6-1029P (83% identical), RNU6-1124P (83% identical), RNU6-12P (83% identical), RNU6-13P (83% identical), and 1288 more.